ENSG00000241573 (zinc finger pseudogene)
Gene: Processed pseudogene on chromosome 7 (129,096,027 to 129,096,735, reverse strand). Ensembl gene ENSG00000241573.
Diseases named in the same sentence as ENSG00000241573 in open-access papers:
ENSG00000241573 is named in the same sentence as 1 disease in open-access papers, as found by Europe PMC text mining. Sharing a sentence is not in itself a finding about the gene and the disease.
ENSG00000241573 shares sentences with these, for which no sentence is quoted: myopia (1 paper).